MAPDA (N6-Methyl-AMP deaminase)
Description:
Deaminase involved in the detoxification of modified adenosines containing N(6)-methylated adenine (m6A) post-transcriptional modification. Modified nucleosides are derived from the degradation of RNAs (mRNAs, rRNAs and tRNAs) and possess intrinsic cytotoxicity and must be cleared to prevent metabolic dysfunction. Acts downstream of ADK and catalyzes the hydrolysis of the free cytosolic methylated adenosine nucleotides N(6)- methyl-AMP (m6AMP), N(6),N(6)-dimethyl-AMP (m6,6AMP) and N(6)- isopentenyl-AMP (i6AMP) to produce inositol monophosphate (IMP). Catalyzes the removal of different alkyl groups not only from N6-substituted purine or 2-aminopurine nucleoside monophosphates but also from O6-substituted compounds in vitro.
Synonyms: HsMAPDA; ADAL
Tractability: Small molecule: a structure with a bound ligand is known; a high-quality ligand is known. PROTAC: ubiquitination databases record sites on it.
Target class: Enzyme; Hydrolase
Gene: Protein-coding gene on chromosome 15 (43,330,307 to 43,355,418, forward strand). Ensembl gene ENSG00000168803.
Subcellular location: Cytoplasm, cytosol
Subcellular location (Human Protein Atlas): Nucleoplasm; Nuclear speckles; Vesicles
Pathways (Reactome):
Drug ADME: Abacavir metabolism
Metabolism: Purine salvage
Gene Ontology:
Molecular function: N6-methyl-AMP deaminase activity; adenosine deaminase activity; deaminase activity
Biological process: toxic metabolite repair; adenosine catabolic process; inosine biosynthetic process
Cellular component: cytosol
Genetic constraint (gnomAD): Loss-of-function variants: 30 observed, 33.8 expected, observed/expected ratio (o/e) 0.89, 90% interval 0.66 to 1.2. The upper end of that interval is the gene's LOEUF score, 1.2, which puts it in group 5 of 6, group 1 being the genes least tolerant of losing a copy. Missense variants: 308 observed, 365.6 expected, observed/expected ratio (o/e) 0.84, 90% interval 0.77 to 0.93. Synonymous variants: 112 observed, 131.1 expected, observed/expected ratio (o/e) 0.85, 90% interval 0.73 to 1.
Homologues: Orthologues: chimpanzee ADAL (99% identical), macaque ADAL (93% identical), dog MAPDA (92% identical), guinea pig MAPDA (90% identical), pig MAPDA (87% identical), rat Adal (84% identical), mouse Adal (83% identical), tropical clawed frog mapda (62% identical), zebrafish mapda (62% identical), Drosophila melanogaster Ada (37% identical), Caenorhabditis elegans adal-1 (33% identical). Paralogues in human: ADA (24% identical), ADA2 (19% identical).
Diseases named in the same sentence as MAPDA in open-access papers:
MAPDA is named in the same sentence as 3 diseases in open-access papers, as found by Europe PMC text mining. Sharing a sentence is not in itself a finding about the gene and the disease.
MAPDA shares sentences with these, for which no sentence is quoted: colorectal cancer (1 paper); pancreatic cancer (1); ulcerative colitis (1).